EGFR (epidermal growth factor receptor)
Diseases named in the same sentence as EGFR in open-access papers (continued):
Sharing a sentence is not in itself a finding about the gene and the disease.
colorectal cancer (continued). "Similarly, while aspirin has antipyretic and analgesic effects and is used in preventing cardiovascular disease, it may also help prevent colorectal cancer by normalizing the expression of epidermal growth factor receptor (EGFR)." (PMID 33101026, 2020). "Moreover, knockdown of EGFR expression could reduce the colony formation, migration and proliferation of colorectal cancer (CRC)." (PMID 32093644, 2020). "Therefore, this study aims to investigate whether FAK is involved in the regulation of colorectal cancer cells through the promotion of EMT via the EGF/EGFR signaling pathway and the enhancement of migration ability." (PMID 32148496, 2020). "Besides, KRAS mutation in colorectal cancer has been reported and KRAS/BRAF genes mutation might make EGFR inhibitors ineffective." (PMID 31998788, 2020). "Approximately, 30%‐50% of colorectal tumors are known to have a mutated KRAS gene, predominantly found in codons 12 and 13, indicating that up to 50% of patients with colorectal cancer may respond to anti‐epidermal growth factor receptor (EGFR) antibody therapy such as cetuximab." (PMID 32329932, 2020). "Distribution of coexisting subclonal mutations in EGFR, KRAS, and NRAS in a subset of the patients with fusion-present colorectal cancer suggests that these fusions may arise as a novel mechanism of resistance to anti-EGFR therapies in patients with metastatic colorectal cancer." (PMID 33015522, 2019). "Colorectal cancers that harbour the same BRAF(V600E) mutation are intrinsically resistant to BRAF inhibitors, due to feedback activation of the epidermal growth factor receptor (EGFR), although double or triple combination trials gave some benefit in terms of response rate." (PMID 31762942, 2019). "Interestingly, the same approach was ineffective in colorectal cancer, where EGFR-mutated status had no predictive power for the anti-EGFR drugs cetuximab and panitumumab." (PMID 30728774, 2019). "Nevertheless, secondary mutations in the extracellular domain of EGFR, mutations in KRAS, NRAS and C-Met, loss of PTEN and activating mutations in PIK3CA, and gain-of-activity in the IGFR pathway have been associated with acquired resistances of some cases of colorectal cancer." (PMID 31508364, 2019). "Indeed, EVs produced by human lung or colorectal cancer cells transfer oncogenic EGFR to cultured endothelial cells, in which they elicit EGFR-dependent responses, including activation of MAPK and AKT pathways, as well as an autocrine production and signaling of VEGF." (PMID 30925923, 2019). "While the role of KRAS gene mutations has been widely accepted for predicting responses to anti-EGFR therapy in patients with colorectal cancer, although this study was based on observation of a single case it gives hope that some KRAS gene mutation may have favorable prognosis." (PMID 28265402, 2017). "Interestingly, EGFR plays major roles in the tumorigenesis of both UC and colorectal cancer." (PMID 27936466, 2017). "The EREG (epiregulin) gene can function as a ligand of EGFR (epidermal growth factor receptor), as well as a ligand of most members of the ERBB (v-erb-b2 oncogene homolog) family of tyrosine-kinase receptors and is known to be associated to diseases like colorectal cancer, and hypopharynx cancer." (PMID 29233967, 2017). "However this strategy may not be generally applied to cetuximab as NRG1 expression was markedly lower in colorectal cancer (CRC), another tumor type where cetuximab is an approved therapy and where EGFR signaling has been implicated." (PMID 28723928, 2017). "Furthermore, the RHBDD1 and EGFR correlation was stronger in late-stage colorectal cancer patients." (PMID 28445956, 2017). "Therefore, RHBDD1 may be useful in colorectal cancer therapy as a therapeutic target in combination with EGFR antibodies." (PMID 28445956, 2017).
colorectal cancer (continued). "Therefore, blocking these cytokines in combination with EGFR targeting agents might represent a promising therapeutic strategy for colorectal cancer patients." (PMID 27708224, 2016). "Thus our hypothesis is that the biological framework of colorectal cancer in women seems to be characterized by Erß signaling, EGFR activation and circadian clock control, all interacting mechanisms, involved in tumour growth." (PMID 27666868, 2016). "Taken together, these data indicate that miRs-134 and -370 are potential tumour suppressor miRNAs and could play a fundamental role in suppressing colorectal cancer tumorigenesis through their ability to co-ordinately regulate EGFR signalling cascade by independently targeting EGFR and PIK3CA." (PMID 27095166, 2016). "Somatic activating mutations in KRAS or NRAS are present in up to 52% of colorectal cancer (CRC), causing constitutive activation of the RAF/MEK/ERK signaling pathway independent of upstream receptor tyrosine kinases like the epidermal growth factor receptor (EGFR)." (PMID 27167191, 2016). "The success of anti-epidermal growth factor receptor (anti-EGFR) therapy for patients of the Kras non-mutation group of colorectal cancer has raised the expectation that other malignancies, such as Kras non-mutation group of ovarian MC can also be treated with comparable success rates." (PMID 27888800, 2016). "However, inhibition of this central signaling molecule in colorectal cancer is only promising when intracellular effectors downstream of EGFR are not altered by activating mutations." (PMID 27064574, 2016). "Finally, in colorectal cancer, the EGFR/RAS pathway is an important signaling pathway." (PMID 25896895, 2015). "The predictive role of BRAF mutation in colorectal cancer is currently debated, but a recent meta-analysis indicated that BRAF mutation is a predictive biomarker of poor prognosis in mCRC patients treated by anti-EGFR monoclonal antibodies, especially in KRAS wild-type patients." (PMID 25983749, 2015). "BRAF p.V600E missense mutation is associated with poor prognosis in colorectal cancer and according to some recent reports, it has negative predictive value in anti-EGFR antibody therapy, though this has yet to reach sufficient levels of evidence to update clinical guidance." (PMID 25568935, 2015). "In colorectal cancer, the presence of the KRAS mutation was associated with upregulation of miR-127-3p, miR-92a, and miR-486-3p and downregulation of miR-378, which constituted a miRNA signature capable of predicting colorectal cancers resistant to EGFR antagonists." (PMID 25874201, 2015). "This clonal evolution hypothesis has been demonstrated after epidermal growth factor receptor (EGFR)-ablative therapy, where a very low number of Kirsten rat sarcoma viral oncogene homolog (KRAS)-mutated colorectal cancer cells emerged to become the dominant clone among the surviving cells." (PMID 26353782, 2015). "However, amplification of EGFR seems to be an uncommon event in colorectal cancer." (PMID 24943349, 2014). "Of interest, overexpression of Transforming growth factor alfa (TGF-α), a specific EGFR ligand, induced EGFR–MET interaction, with subsequent MET phosphorylation and activation of downstream effectors in EGFR-independent manner causing cetuximab resistance in colorectal cancer cells." (PMID 28548075, 2014). "In contrast, colorectal cancers with this mutation do not respond to therapies targeting this specific BRAF mutation as a result of feedback activation of the epidermal growth factor receptor (EGFR)." (PMID 24782526, 2014). "However, such cases may be considered for the combination therapy targeting both EGFR and BRAF, as had been described in a patient with BRAF V600E mutated colorectal cancer." (PMID 25415047, 2014).
colorectal cancer (continued). "v-Ki-ras2 Kirsten rat sarcoma viral oncogene homolog (KRAS) genotyping is required prior to anti-epidermal growth factor receptor monoclonal antibody therapy administered in cases of metastatic colorectal carcinoma (CRC)." (PMID 24765171, 2014). "Furthermore, EGFR mutations are rare (<1%) in colorectal cancer and had no influence on anti-EGFR response in mCRC and therefore cannot be used to predict the clinical response to anti-EGFR monoclonal antibodies." (PMID 24133623, 2013). "However, assessment of EGFR expression can be affected by immunoreactivity of normal tissues, differential EGFR reactivity of neoplasms from different areas of the bowel, and heterogeneity of reactivity within the colorectal carcinoma itself." (PMID 23824671, 2013). "Although several previous reports demonstrated the association between EREG (and/or AREG) expression and survival time in KRAS wild-type patients who had received Cetuximab, no previous paper reported the association in colorectal cancer patients who had never received anti-EGFR antibody." (PMID 22409860, 2012). "For example, although epidermal growth factor receptor (EGFR) expression as measured by immunohistochemistry is not helpful in selecting patients for anti-EFGR mAb therapy in advanced colorectal carcinoma, excluding those with mutated K-ras has become helpful in clinical practice." (PMID 21811498, 2012). "However, to date, only very few, mainly non-European, studies have reported rare EGFR mutations in colorectal cancer (CRC)." (PMID 22026926, 2011). "In conclusion, missense mutation, which may be responsible for an activation of the EGFR gene through amino acid substitution, seems not to play a major role in the occurrence and development of colorectal cancer." (PMID 22026926, 2011). "Specific alterations of the EGFR gene, including copy number variations, and oncogenic activation of EGFR downstream effectors such as KRAS and BRAF had been previously reported as the genetic events underlying the response to cetuximab plus chemotherapy in colorectal cancer." (PMID 22152101, 2011). "Hence, EGFR might be involved in the development of colorectal cancer and has now been validated as a clinically relevant target." (PMID 22026926, 2011). "However, the clinical significance of EGFR overexpression in colorectal cancer is uncertain." (PMID 21403829, 2011). "However, data about EGFR gene silencing by promoter methylation are substantially lacking and may help clarifying the role of this epigenetic mechanism on colorectal cancer biology." (PMID 21559018, 2011). "We believe that EGFR promoter hypermethylation, after confirmation in larger data set, may represent a valuable and important asset to be considered in further studies investigating the role of EGFR as a therapeutic target in colorectal cancer patients." (PMID 21559018, 2011). "Recently a number of randomized trials have shown that treatment of patients with advanced colorectal cancer (CRC) do not benefit from therapies targeting the epidermal growth factor receptor (EGFR) when their tumors harbor mutations in the KRAS, BRAF and PIK3CA genes." (PMID 20098682, 2010). "Loss of phosphatase and tensin homologue deleted in chromosome 10 (PTEN) function in advanced colorectal cancer (CRC) may represent one of the resistance mechanisms to cetuximab by interfering with the epidermal growth factor receptor signal transduction pathway." (PMID 19953097, 2010). "Furthermore a previous report also suggested that EGFR GCN analysis may help identifying responding patients among wild-type colorectal cancer patients." (PMID 19712476, 2009). "Although recent studies have shown a significant association between the response to cetuximab treatment and EGFR amplification or K-ras mutations in colorectal cancer, none of the patients in the present study exhibited increased EGFR gene copy number (EGFR/CEP7 >2.0) or K-ras mutations." (PMID 19127259, 2009).
colorectal cancer (continued). "In our study, the expression of EGFr has been evaluated using three different molecular techniques that provide quantitative information that, in our opinion, may be a more accurate and reliable study of EGFr status in colorectal cancer as a predictor of response to EGFr inhibitors." (PMID 18827815, 2008). "Hence, the blockade of EGFR is a promising strategy to improve colorectal cancer treatment." (PMID 18182978, 2008). "This review summarizes current evidence from pivotal phase II and III clinical trials, translational studies, and real-world data evaluating EGFR-, BRAF-, and HER2-directed therapies in colorectal cancer." (PMID 41899309, 2026). "Genetic alterations in BRAF are common in colorectal cancer, alongside others like KRAS, which predicts resistance to epidermal growth factor receptor (EGFR) monoclonal antibodies." (PMID 40942081, 2025). "The overexpressed siRS-7 activated the downstream oncogenes EGFR and RAF1 of miR-7 by inhibiting miR-7, which made colorectal cancer more aggressive." (PMID 39959665, 2025). "EGFR and its downstream signaling pathways (including the PI3K/AKT pathway) play a key role in the development and progression of colorectal cancer." (PMID 40832614, 2025). "In colorectal cancer, we and others observed that inhibiting Mitogen-Activated Protein Kinase Kinase (MEK) rapidly activates the epidermal growth factor receptor (EGFR), which synergistically enhances AKT signaling." (PMID 40419504, 2025). "Osimertinib (OSI), an epidermal growth factor receptor tyrosine kinase inhibitor (EGFR-TKI), has been found to upregulate MCT1 expression in colorectal cancer (CRC) cells." (PMID 40612939, 2025). "We previously assessed the effects of afatinib, both as a monotherapy and in combination with standard cytotoxic agents or the anti-EGFR monoclonal antibody ICR62, on a panel of human colorectal cancer cell lines." (PMID 40940907, 2025). "Our study identifies USP11 as a key regulator of colorectal cancer (CRC) progression, acting through two primary signaling pathways: the EGFR and TLR pathways." (PMID 41419456, 2025). "Anti-EGFR therapies are used for other tumor types, including colorectal cancers (CRCs) with wt RAS and BRAF, which are treated with anti-EGFR monoclonal antibodies, such as cetuximab or panitumumab." (PMID 40846697, 2025). "Background and Objectives: KRAS genes are among the most prominent oncogenes that trigger tumor formation in colorectal cancer (CRC) and serve as predictive biomarkers for resistance to anti-EGFR therapies in metastatic colorectal cancer (mCRC) patients." (PMID 40282985, 2025). "IGF2BP3 functions as an m6A reader to stabilize and enhance translation of EGFR mRNA through collaboration with METTL14, thereby activating EGFR signaling and conferring therapeutic resistance to cetuximab in colorectal cancer." (PMID 40986143, 2025). "EGFR activation in myeloid cells increases STAT3 phosphorylation and IL‐6 expression, promoting colorectal cancer cell proliferation." (PMID 40859900, 2025). "Examples include EGFR/IL13Rα2 CAR-T for GBM, CD19/GCC “Coupled CAR” for colorectal cancer (CRC), and TAG - 72/ΔCD47m CAR for ovarian cancer." (PMID 40969260, 2025). "For example, we observed genetic interactions between BRAF and EGFR, which is important in the BRAF-mutant colorectal cancer cell line HT-29." (PMID 41353404, 2025). "Finally, G13D—while less frequently discussed—represents a non-negligible subset of RAS mutations, especially in colorectal cancer, where it may respond differently to anti-EGFR therapies compared with other mutations." (PMID 39941797, 2025). "The epidermal growth factor receptor (EGFR) plays a critical role in the development and progression of colorectal cancer (CRC)." (PMID 40510154, 2025). "Among the synthesized compounds, C4 and G4 exhibited significant cytotoxic effects against HT-29 colorectal cancer cells, achieving IC50 values of 0.9 μM for EGFR and 0.5 μM for COX-2, respectively." (PMID 41149466, 2025).
colorectal cancer (continued). "A primary focus is on overcoming therapeutic resistance, particularly in colorectal cancer, where the initial failure of single-agent BRAF inhibitors led to the discovery that feedback activation of EGFR reactivates the pathway." (PMID 41361128, 2025). "Currently, cetuximab is the only EGFR monoclonal antibody approved by the Food and Drug Administration (FDA) for the treatment of colorectal cancer, with others, such as panitumumab and matuzumab, undergoing clinical development." (PMID 40722718, 2025). "In patients with colorectal cancer (n = 67,959), the HRs for ATE were 1.25 (95% CI: 1.02–1.52) with VEGF-targeted therapy (n = 6769) and 1.38 (95% CI: 1.07–1.79) with EGFR-targeted therapy (n = 3932)." (PMID 40896464, 2025). "The progression of solid tumors is highly dependent on the epidermal growth factor receptor (EGFR) pathway, and cetuximab that targeting EGFR have demonstrated significant efficacy in advanced colorectal cancer and head and neck cancer." (PMID 41291854, 2025). "Specifically, it was described that, in colorectal cancer cell lines, the inhibition of KRASG12C induces a greater rebound of phospho-ERK compared to NSCLC cells, with reactivation of EGFR." (PMID 40141164, 2025). "The effect of FA (100–250 μg/mL) on a colorectal cancer cell line (HCT-15), as well as on epidermal growth factor receptor (EGFR) gene expression, was also investigated." (PMID 40076243, 2025). "In colorectal cancer, PRMT1 cooperates with chromatin subfamily A member 4 (SMARCA4) to activate EGFR signaling, promoting malignant transitions." (PMID 40612681, 2025). "Ongoing trials include adagrasib plus cetuximab for KRAS G12C in colorectal cancer (CRC) (phase III) and BLU-945, a fourth-generation EGFR inhibitor, for osimertinib-resistant NSCLC (phase I/II)." (PMID 40547482, 2025). "Amphiregulin (AREG), a principal ligand of the epidermal growth factor receptor (EGFR, also known as ErbB1), plays a critical role in colorectal carcinoma by driving tumor cell proliferation, survival and resistance to therapy." (PMID 41515404, 2025). "Preclinical data from tumors with high EGFR expression, such as head and neck squamous cell carcinoma (HNSCC) and colorectal carcinoma, further support the potential application of the EGFR/CD3 bispecific antibody in cSCC." (PMID 41333481, 2025). "The overexpression of EGFR and HER2 has been reported to have significant impacts on the colorectal cancer (CRC) development and metastasis." (PMID 39220126, 2024). "Synergy between small-molecule inhibitors of EGFR and AURKA was first identified in a synthetic lethality screen performed in EGFR-overexpressing head and neck squamous cell carcinomas and colorectal cancers." (PMID 38639476, 2024). "Targeting the epidermal growth factor receptor (EGFR), it is used for the treatment of metastatic-colorectal cancer and head and neck cancer." (PMID 39185413, 2024). "Given the significance of ErbB receptors in human cancers, inhibitors targeting ErbB have been approved for cancer treatment, such as Cetuximab (Erbitux), which targets EGFR and is used to treat advanced colorectal cancer." (PMID 39479720, 2024). "Patients with class I V600EBRAF-mutant (MT) colorectal cancer exhibit a poor prognosis, and their response to combined anti-BRAF/EGFR inhibition remains limited." (PMID 39083088, 2024). "In colorectal cancer (CRC) in particular, the EGFR signaling pathway is frequently hyperactivated via receptor and/or ligand overexpression and downstream oncogenic mutations." (PMID 40727266, 2024). "Involvement of the AhR-regulated MMP-1/EGFR signaling in colorectal cancer pathogenesis was indicated as the suppression of MMP-1, a gene induced by AhR, led to the improvement of colorectal cancer by inhibiting EGFR-downstream PI3K/AKT signaling." (PMID 39211042, 2024). "Evidence indicates that combinations of anti‐EGFR antibodies and KRAS p.G12C (c.34G>T) inhibitors can be an effective treatment strategy for advanced colorectal cancer." (PMID 39039804, 2024).